CAV1 (caveolin 1)
Diseases named in the same sentence as CAV1 in open-access papers (continued):
Sharing a sentence is not in itself a finding about the gene and the disease.
tumor (continued). "Tumor-supportive oncometabolism studies stated that Cav-1 enables re-modification of cancer cell lipid metabolism toward increased sphingomyelins catabolism to ceramide derivatives and changes ceramide metabolism in cancer cells." (PMID 36837801, 2023). "Caveolin-1, the best-characterised isoform of this family in terms of its roles in cancer, can function either as tumour suppressor or tumour promoter depending on the cancer type, cellular context and conditions." (PMID 37629086, 2023). "CAV1 plays an oncogenic role in solid tumors, and its expression correlates negatively with tumor invasion." (PMID 37124501, 2023). "Insufficient caveolin-1 is able to induce carcinogenesis, and downregulation of caveolin-1 enhances tumor cell invasion and metastasis." (PMID 37576808, 2023). "A loss of stromal Cav1 also predicts progression to invasive disease in DCIS (ductal carcinoma in situ) patients, suggesting that a loss of Cav1 regulates tumor progression." (PMID 37822942, 2023). "Caveolins (Caveolin-1, 2, and 3) are scaffold proteins composed of cholesterol-enriched microdomains and play an essential role in tumor progression." (PMID 37174125, 2023). "Together, these results show that invadosome disruption (by SH3PXD2A or CAV1 KD) consequently impacts the ability of tumour cells to remodel the environing collagen network." (PMID 37903910, 2023). "In cancer, Cav-1 mainly participates in various processes, including cell transformation, tumor growth, invasion and metastasis, multidrug resistance, and angiogenesis." (PMID 37143134, 2023). "In specific cancers including breast, lung, colon, and ovarian, Cav1 is expressed in low levels, which is maintained throughout the process of tumor cell proliferation and metastasis." (PMID 37998001, 2023). "CAV1 promotes tumor angiogenesis and mediates the unlimited proliferation and self-renewal of tumor stem cells at the initiation stage of malignancy." (PMID 37907864, 2023). "The study analyzing CAV1 methylation 206 kb downstream of our sequence (chr7:116,730,563- 116,730,672) showed that methylation was the highest in PCa tissue, lower in tumor-adjacent tissue, and the lowest in NTT for nine of ten analyzed CpGs." (PMID 36036057, 2023). "Caveolin-1 (CAV1) is a membrane-bound protein that suppresses tumor development yet also promotes metastasis." (PMID 38069269, 2023). "In this study, we report that LY6K‐depletion suppresses the effect of TGF‐β on invasiveness and EGF‐stimulated proliferation of tumor cells by repressing clathrin‐ and CAV‐1‐mediated endocytosis." (PMID 37076981, 2023). "After COL1A1 knockout, Western blot was employed to examine the expression of fibrosis-related proteins (E-cadherin, α-SMA, FAP, and Cav-1) in the tumor microenvironment, aiming to determine any alterations in matrix fibrosis levels." (PMID 38045487, 2023). "Cav1 is secreted by PCa cells and observed in the serum of PCa patients, showing a trend of positive correlation with tumor stage and grade." (PMID 37910338, 2023). "Stromal cells abundantly express CAV1, and changes in CAV1 expression in the tumor stroma have been broadly reported." (PMID 35158857, 2022). "On the other hand, high expression of caveolin-1 in mitochondria inhibits the proliferation of H-Ras-driven tumor cells." (PMID 35064107, 2022). "Functionally, the augmented expression in tumor cells with low basal levels of CAV-1 reduced COX-2 mRNA and protein levels, beta-catenin-Tcf/Lef and COX-2 gene reporter activity, PGE2 production, and cell proliferation." (PMID 36471782, 2022). "CAV1 is also expressed in the stromal compartment and can be considered a marker of the tumor microenvironment (TME)." (PMID 35660849, 2022). "Normal human gingival fibroblasts, primed with the tumor microvesicles, exhibited a phenotype switch to cancer-associated fibroblasts (CAF) and underwent a degradation of caveolin-1 (CAV1)." (PMID 35498409, 2022).
tumor (continued). "The present study results are contrary to most results in humans, as they indicate that high expression values of Caveolin-1 can indicate a favorable tumor biological behavior, as they were inversely correlated with MC." (PMID 36299636, 2022). "In vitro and in vivo, elevated caveolin-1 expressions in metastatic mice and human PCa cells have been reported, suggesting that inhibition of apoptosis promotes tumor progression." (PMID 35747825, 2022). "Aberrant CAV-1 expression has been reported in several types of cancers and CAV-1 expression level sometimes depends on the tumor’s pathological subtype or clinical staging." (PMID 36532050, 2022). "It has been reported that low expression of CAV1 favors tumor progression by promoting cell proliferation, angiogenesis, and metastasis, although re-expression of CAV1 can be detected in later tumor stages." (PMID 35719407, 2022). "Samples obtained from patients enrolled on Trastuzumab trials (9/46 tumor samples were from patients that received other therapies prior to Trastuzumab) were analyzed for CAV1 IHC." (PMID 35534471, 2022). "First, the expression of Cav-1 is modulated in tumors and in tumor stroma and those modulations are connected with progression of several cancers." (PMID 36439249, 2022). "These examples emphasize the importance of CAV1 expression in regulating the metabolism of cells in the tumor stroma environment and how this can affect cancer cell behavior." (PMID 35740528, 2022). "CAV1 as structural organizer generally regulates plasma membrane microdomain formations and thus, modulates signaling pathways to promote tumor and progression and potentially therapy resistance." (PMID 35155239, 2022). "Phosphorylated Cav-1 reciprocally enhances RhoA activity and facilitates focal adhesion turnover, leading to enhanced tumor cell migration." (PMID 35954304, 2022). "We found that the protein levels of CXCL9 and CXCL10 were obviously elevated, and the protein level of caveolin-1 was downregulated in the tumor cells of mice treated with anti-GD2 mAb plus MβCD compared with the other three groups." (PMID 36284313, 2022). "Nevertheless, different studies have produced opposite data, Cav-1 being considered either as a tumor suppressor or an oncogene." (PMID 36439249, 2022). "In vivo, a combination of anti-CAV1 antibody treatment along with dasatinib or sunitinib demonstrated significant tumor regression when compared to the drug treatment alone, suggesting the importance of drug combinations in overcoming treatment resistance." (PMID 35158857, 2022). "Thirty tumor samples were obtained, and Caveolin-1, GATA-3, and Ki67 expression was assessed by immunohistochemistry and associated with pathological factors by univariate and multivariate analyses." (PMID 36299636, 2022). "The function of CAV-1 as an oncogene or tumor suppressor in cancer progression remains controversial." (PMID 36532050, 2022). "CAV1 modulates many cellular functions, including nutrient and drug internalization, tumor-stroma interactions, hypoxia response, inflammation, epithelial-mesenchymal transition (EMT), and cell cycle regulation." (PMID 35660849, 2022). "On the other hand, CAV1 acts as a tumor suppressor in some cases, as its low expression favors tumor progression." (PMID 36233075, 2022). "Meanwhile, the tumor sphere formation ability of BCCs was enhanced after transfection with siRNA308 to block CAV-1 expression in the co-cultured fibroblasts compared with that in the BCCs in the single culture and ESF-NC groups." (PMID 36604141, 2022). "Co-expression of CAV1 and E-cadherin reduces tumor formation by sequestering β-catenin in a plasma membrane complex and thereby downregulating β-catenin/Tcf/Lef transcriptional activity." (PMID 35740528, 2022). "On the first list, caveolin-1 represents a multifunctional protein that orchestrates many changes both in the tumor microenvironment/malignant cell crosstalk and intracellular functions." (PMID 36430209, 2022).
tumor (continued). "In conclusion, the prognostic impact of CAV1 was highly dependent on its localization, anthropometric, and tumor factors." (PMID 35660849, 2022). "CAV-1 is also an important regulator of several cell signaling pathways and plays an important role in malignant cell transformation, tumor growth, angiogenesis and metastatic processes." (PMID 36556936, 2022). "TGF-β1 has been found to be upregulated in tumor cells that approach the nerve, which enhances the production of cav-1 in the perineurium of nerves, and cav-1 secretion, in turn, prevents tumor cells from apoptosis." (PMID 36077602, 2022). "Knocking down CAV1 increases the amount of cholesterol and testosterone in fibroblasts and promotes cancer-cell proliferation, primary tumor growth, and metastasis." (PMID 35158857, 2022). "For instance, exosomes from the tumor cells under hypoxia can upregulate caveolin-1 (CAV1), which is responsible for CAF-like differentiation." (PMID 36109501, 2022). "Studies have shown that gefitinib can effectively inhibit the conduction of the EGF signaling pathway, and overexpression of Cav1 in tumor cells can reduce the inhibitory effect of gefitinib." (PMID 36699336, 2022). "Previous studies of HER2-positive tumor models implied a role for CAV1 in antibody binding and efficacy." (PMID 35534471, 2022). "The studies also revealed that caveolin-1 and c-Myc are favorable molecular targets in tumor cells and metastasis." (PMID 35495123, 2022). "To this end, we first established the significance of CAV1 levels on TDM1-tumor binding using HER2+ gastric PDXs (78% of PDXs were obtained from patients prior initiating Trastuzumab)." (PMID 35534471, 2022). "To date, it has been found that TAFs expressing immunoglobulin superfamily containing leucine rich repeat (ISLR) or Caveolin-1 (CAV-1) can inhibit tumor progression." (PMID 35410257, 2022). "The cluster of patients with worse overall survival was characterised by high expression of lactate-related transporters as well as high ACTA2 and CAV1 expression in tumorous tissues." (PMID 35565415, 2022). "Instead, transient and controlled CAV1 depletion using statins boosts TDM1-tumor binding and internalization while reducing ADC recycling." (PMID 35534471, 2022). "Perhaps more important is the correlation of Cav-1 tyrosine phosphorylation with enhanced tumor cell migration and metastasis." (PMID 35954304, 2022). "In contrast, low expression of caveolin-1, a tumor-suppressor gene, in CAFs predicts adverse outcomes in GC, showing that caveolin-1 in CAFs is probably a useful negative prognostic marker." (PMID 36244987, 2022). "Cav1 expression has been reported to be abnormally changed in a wide range of malignancies, with growing evidence pointing to Cav1 overexpression, especially at higher tumor stages." (PMID 36121548, 2022). "CAV1 was already suggested to function as an androgen receptor co-regulator at advanced tumor stages." (PMID 35155239, 2022). "Emerging evidence has shown that the scaffold domain of Cav-1 (CSD) plays a key role in tumor progression and cellular metabolic reprogramming." (PMID 34955837, 2021). "Although several studies have shown that Cav-1 can serve as a tumor oncogene, and induces tumor progression, other studies confirmed the role of Cav-1 as a tumor suppressor." (PMID 33774714, 2021). "Cells with a high catulin reporter GFP expression at the tumor invasion front were also positive for CAV1 protein (A′)." (PMID 35008571, 2021). "This characteristic epithelial-stromal CAV1 shift was found to be functionally relevant to tumor progression and correlated with reduced overall survival." (PMID 33868995, 2021). "Altogether, the data suggest that Cav1 expression is correlated with tumor recurrence and poor prognosis." (PMID 34207120, 2021). "We report here the higher expression of Cav-1 within the peri-necrotic and pseudo-palisading areas of the GB tumour, areas also expressing high levels of HIF-1α factor." (PMID 34490102, 2021).
tumor (continued). "Caveolin-1 (Cav-1) has been shown to act variously as both a tumour suppressor and tumour promoter in many cancers." (PMID 34490102, 2021). "Conclusively, we provide further and new evidence that the characteristic shift in stromal‐epithelial CAV1 being functionally relevant to tumor progression even occurs in penile SCC." (PMID 33868995, 2021). "More meaningfully, the upregulation of CAV-1 is related to advanced tumor stage, lymph node metastasis and poor prognosis of cancer patients." (PMID 33935779, 2021). "Tumor epithelial Cav-1 expression averaged 8-fold higher than adjacent stroma (mean 2.56 vs 0.29, p = 8.7x10-19) while benign ovarian epithelium had 2.5 fold higher expression compared to normal stroma (mean 3.06 vs. 0.88, p = 3.7x10-9)." (PMID 34813586, 2021). "We showed that Cav1 confers resistance, allowing cells to survive, proliferate or escape tumor spheroids even under extreme conditions, such as the CTX-radiotherapy regimens used in the clinical management of LA-HNSCC." (PMID 34207120, 2021). "Gene set enrichment analysis (GSEA) showed the role of AREG, STAG3 and CAV1 in dysregulated pathways of tumor." (PMID 33712015, 2021). "Even within the tumor stroma, CAV1 expression was hardly detectable and predominately restricted to the vascular compartment (#1-3, asterisks)." (PMID 33868995, 2021). "Ig-like domain 2 has been described to bind with cyclophilins important in the regulation of inflammatory responses and caveolin-1, which is also linked to MMP induction and tumor invasion." (PMID 34421910, 2021). "As a key structural protein of caveolin, caveolin-1 (CAV1) is considered as a candidate tumor suppressor gene 11,12." (PMID 34234869, 2021). "Meanwhile, CAV1 is induced in the tumour stroma of several cancer types and showed significantly induced expression in the established primary colon CAFs." (PMID 33802764, 2021). "Similar to the IHC analysis, the expression of Cav-1 in benign stroma was significantly higher than in the tumor stroma, with median AQUA® scores of 308.9 and 152.6, respectively (p = 8.3x10-13)." (PMID 34813586, 2021). "In recent decades, increasing attention has been paid to the expression of caveolin-1 (Cav-1) in the tumor microenvironment." (PMID 33531603, 2021). "In contrast, Cav-1 was less highly expressed in the following zones: leading-edge (LE), infiltrating tumour (IT) and in cellular tumour (CT; defined where tumour cells exceed normal cells ~100–500-fold)." (PMID 34490102, 2021). "We identified that hnRNPA1 loaded batched tumor-promoting miRNAs into sEVs with the assist of caveolin-1 (CAV1) in A549 cells." (PMID 34222256, 2021). "EVs carrying caveolin-1 can construct a pseudo hypoxic environment and contribute to tumour growth and migration." (PMID 33478586, 2021). "Based on our current investigation caveolin-1 plays an immensely important role in radio-resistance and tumor aggression." (PMID 34762666, 2021). "The function of Cav-1 in tumor cells seems to be highly context-dependent exerting both tumor suppressive and oncogenic effects." (PMID 33774714, 2021). "Endothelium did show positive Cav-1 staining, which was of a strong intensity in the tumour sections (arrow) but of lower intensity (25%) within endothelial cells of non-tumour brain cortex tissue (magnification I) in normal brain cortex tissue." (PMID 34490102, 2021). "In contrast, there was no gender-based adverse outcome on survival in patients whose tumours expressed low levels of Cav-1, i.e. median survival (M) 427 days vs (F) 419 days (HR= 1.471, P=0.066)." (PMID 34490102, 2021). "Viral interleukin-6 promotes cell proliferation, tumor invasion, and angiogenesis by suppressing caveolin 1, which plays a role in tumor development mediated by DNA methyltransferase 1 (DNMT1)-targeted STAT3 acetylation." (PMID 35008848, 2021).
tumor (continued). "They showed expression levels of HIF-1α and Cav-1 to be upregulated in IDH-wild type tumours, and Cav-1 levels to be significantly correlated with high HIF-1α expression." (PMID 34490102, 2021). "Gene set enrichment analysis showed the role of AREG, STAG3 and CAV1 in dysregulated pathways of tumor." (PMID 33712015, 2021). "In contrast, CAV1 expression within the tumor stroma was decreasing with upon tumor progression (Figures 4and5)." (PMID 33868995, 2021). "The interaction between gp60 and caveolin-1, which is upregulated in many cancer types aids the vesicle formation, facilitating the accumulation of albumin in the tumor mass." (PMID 33842184, 2021). "Low tumour purity was associated with high expression of MYH11, RICTOR and CAV1, which are markers for mesenchymal lineage or EMT." (PMID 35083216, 2021). "Conversely, TIMP3 (P = 0.0156), THBS1 (P = 0.0156), and CAV1 (P = 0.0313) were all decreased in tumour stroma EVs compared to normal stroma EVs." (PMID 34596356, 2021). "Conversely, Cav-1 expression was higher in OvCa stroma compared to tumor epithelium with IF (p = 0.002)." (PMID 34813586, 2021). "A loss of stromal CAV1, when epithelial CAV levels seem to increase, was further confirmed at advanced tumor stages." (PMID 33868995, 2021). "A strong tumor epithelial CAV1 immunoreactivity as shown by the high CAV1 scores correlated with low CAV1 contents within the tumor stroma." (PMID 33868995, 2021). "Although HER2 was present in caveolin-1-positive microdomains, it was also observed that tumor cells with high caveloin-1 expression contained HER2 clusters below the cell surface." (PMID 34358100, 2021). "A combination of caveolin-1 and Sox-2 protein levels was sufficient to maintain high predictive accuracy, which we validated in tumor samples from patients with HNSCC with known clinical response to cetuximab." (PMID 34546978, 2021). "Relating the expression of the two isoforms of Cav-1 in the CAFs to the tumor stages of the patients, they showed an increased Cav-1α expression associated with an advanced tumor stage (p = 0.007)." (PMID 33774714, 2021). "Hypoxia induces tumour cells or CAFs to secrete caveolin-1, through trafficking by extracellular vesicles, and contributes to tumour development." (PMID 33478586, 2021). "In contrast, tumor cells with low caveolin-1 expression contained HER2 expression predominantly at the cell surface." (PMID 34358100, 2021). "The role of Cav-1 in malignancy is however both complex and multifaceted with both tumour suppressor and oncogenic properties." (PMID 34490102, 2021). "To verify if the expression of CAV1 protein correlated with the tumor stage of different HNSCC cells, we performed immunohistochemical analysis of CAV1 on a human tissue microarray slide panel." (PMID 35008571, 2021). "The same effect was also observed when Caveolin-1 was overexpressed, confirming, as previously reported, that Caveolin-1 contributes to the tumor suppressor activity of DLC1." (PMID 34727930, 2021). "Among eight samples with moderate IHC expression of Cav-1 in the tumor epithelium (Hscore = 3), we observed a wide range of AQUA scores (range = 88–257)." (PMID 34813586, 2021). "When EGFR is activated, caveolin-1, which inhibits anoikis and promotes tumor metastasis, is also activated, and Src, a signaling transducer, subsequently activates Akt to promote cancer cell and tumor proliferation." (PMID 34094906, 2021). "We then identified the genes whose tumour expression correlated (either positively or negatively) with Cav-1 (False Discovery Rate correction at a p-value of < 0.01)." (PMID 34490102, 2021). "We found female patients expressing high tumour levels of Cav-1 displayed a significantly shorter median survival time compared to male patients expressing high levels of Cav-1 (median survival 90.5 days vs 320 days: HR= 3.145)." (PMID 34490102, 2021).